PDGFD (platelet derived growth factor D)
Diseases named in the same sentence as PDGFD in open-access papers (continued):
Sharing a sentence is not in itself a finding about the gene and the disease.
Stroke (5 papers, 2012 to 2025). Sudden impairment of blood flow to a part of the brain due to occlusion or rupture of an artery to the brain. "To test this hypothesis, we investigated the association of genetic variants in PDGFD with the risk of first-ever ICH in a large case-control stroke study in China." (PMID 22289441, 2012). "We hypothesized that genetic variation in PDGFD gene might alter the susceptibility to stroke." (PMID 22289441, 2012). "However, the associations of PDGFD variants with other type of stroke, especially ICH have not been investigated." (PMID 22289441, 2012).
bladder cancer (4 papers, 2021 to 2024). "Meanwhile, PDGFD was an important predictor gene for bladder cancer, renal clear cell carcinoma, and osteosarcoma." (PMID 35847907, 2022). "In the current study we correlated NRP, PDGFC and PDGFD messenger expression with clinical outcomes in bladder cancer." (PMID 33918816, 2021).
coronary artery disease (4 papers, 2016 to 2023). "Additionally, a genome-wide association study revealed that SNPs in the PDGFD locus are related to CAD (Coronary Artery Disease (C4D) Genetics Consortium, 2011)." (PMID 33381146, 2020).
Hepatic fibrosis (4 papers, 2015 to 2022). The presence of excessive fibrous connective tissue in the liver. "Furthermore, an interesting key regulator such as PDGFD (platelet-derived growth factor D), an important regulator and therapeutic target for hepatic fibrosis, was found to be upregulated as well." (PMID 35897797, 2022). "Ten DEGs including PDGFra, PDGFrb, PDGFb, PDGFd, COL1A1, COL1A2, COL5A2, ITGA5, THBS1 and IL1R1, closely related to liver fibrosis, were chosen for the real-time qRT-PCR analysis." (PMID 26691002, 2015). "HQD down-regulated the expressions of PDGFra, PDGFrb, PDGFb, PDGFd, COL1A1, COL1A2, COL5A2 and THBS1, and TGF-β and PDGF signaling pathways in the DMN-induced liver fibrosis in rats." (PMID 26691002, 2015).
hepatocellular carcinoma (4 papers, 2013 to 2023). A malignant tumor that arises from hepatocytes. "Platelet-derived growth factor-D (PDGF-D) pathway was involved in the acquisition of EMT characteristics of gemcitabine resistant hepatocellular carcinoma cells." (PMID 27016414, 2016). "Emerging evidence demonstrates that platelet-derived growth factor-D (PDGF-D) plays a critical role in epithelial-mesenchymal transition (EMT) and drug resistance in hepatocellular carcinoma (HCC) cells." (PMID 25760076, 2015).
ischemic stroke (3 papers, 2012 to 2024). A stroke disorder caused by obstruction of blood flow to the brain, due to thrombotic (local blood clot formation) or embolic (due to a blood clot or other material traveling from another site) event. "More importantly, a case-control study demonstrated an association between PDGFD gene polymorphisms and ischemic stroke." (PMID 36118760, 2022).
Obesity (3 papers, 2021 to 2024). Accumulation of substantial excess body fat. "In addition, obesity-related PVAT dysfunction reportedly promotes Ang II-induced aortic aneurysm formation by secreting platelet-derived growth factor-D (PDGF-D)." (PMID 34456867, 2021). "Recently, platelet derived growth factor-D (PDGF-D) was reported to be highly expressed in aPVAT of obese mice, and this enhanced expression accelerated adventitial fibrosis and inflammation during obesity-related AAA formation." (PMID 39156105, 2024).
osteosarcoma (3 papers, 2021 to 2024). A usually aggressive malignant bone-forming mesenchymal neoplasm, predominantly affecting adolescents and young adults. "Little is known about PDGFD in osteosarcoma other than it had predictive power for the chemotherapy response." (PMID 38652223, 2024). "A transwell assay was utilized to investigate PDGFD’s effects on metastatic capacity in primary osteosarcoma cells in vitro." (PMID 38652223, 2024). "PDGFD displayed an inhibitory effect on osteosarcoma metastasis, likely through the suppression of the EMT signaling pathway." (PMID 38652223, 2024). "Manipulation of PDGFD expression in primary osteosarcoma cells examined invasion abilities and related markers." (PMID 38652223, 2024). "Furthermore, transwell assays and RT-qPCR assays were conducted using osteosarcoma primary cells to confirm that PDGFD potentially inhibits osteosarcoma metastasis via the EMT pathway." (PMID 38652223, 2024). "Nonetheless, the precise interaction between osteosarcoma and fibroblasts remains unclear, necessitating further investigation into the downstream pathway of PDGFD-PDGFRB." (PMID 38652223, 2024). "However, this study provides preliminary evidence supporting the inhibitory effect of PDGFD on osteosarcoma metastasis." (PMID 38652223, 2024). "The distribution of PDGFD and PDGFRB in osteosarcoma were consistent with their distribution in Rhabdomyosarcoma." (PMID 38652223, 2024). "and found that PDGFD was mainly expressed in osteosarcoma cells, while the PDGFRB expression was observed in both osteosarcoma cells and stromal cells." (PMID 38652223, 2024). "PDGFD positivity was significantly higher in non-metastatic osteosarcoma primary lesions than metastatic primary lesions (81.67% ± 21.58% vs. 43.89% ± 33.15%, p = 0.0214)." (PMID 38652223, 2024). "Immunohistochemistry demonstrated considerably greater PDGFD expression in non-metastatic osteosarcoma tissues and organoids, correlating with extended metastasis-free and overall survival." (PMID 38652223, 2024). "Manipulating PDGFD expression demonstrated altered invasive abilities and marker expressions in primary osteosarcoma cells from both non-metastatic and metastatic lesions." (PMID 38652223, 2024). "scRNA-seq data analysis revealed that PDGFD expression levels were significantly higher in non-metastatic osteosarcoma, compared with metastatic samples." (PMID 38652223, 2024). "This study utilized scRNA-seq analysis to identify the presence of PDGFD in non-metastatic osteosarcoma." (PMID 38652223, 2024). "Conversely, the overexpression of PDGFD, in either non-metastatic osteosarcoma or metastatic osteosarcoma, resulted in a decrease in MMP9, β-catenin, and ZEB expression, while E-cadherin expression was increased." (PMID 38652223, 2024). "The identified immune-related predictive signature, including CD70, TNFRSF9, EGFR, PDGFD and S100A6, will facilitate the development of personalized therapy for osteosarcoma and provide new insights into the role of the tumor immune microenvironment in regulating patients’ responses to chemotherapy." (PMID 34016089, 2021). "the downregulation of PDGFD, regardless of non-metastatic osteosarcoma or metastatic osteosarcoma, led to a significant upregulation of matrix metallopeptidase 9(MMP9), β-catenin, and zinc finger E-box binding homeobox (ZEB) expression, while E-cadherin expression was downregulated." (PMID 38652223, 2024). "IHC was used to detect PDGFD and PDGFRB expression in non-metastatic and metastatic osteosarcoma primary lesions." (PMID 38652223, 2024). "Additionally, organoids of both non-metastatic and metastatic osteosarcoma were constructed, and immunohistochemistry and multicolor immunofluorescence techniques were employed to validate the distributional characteristics, expression, and ligand-receptor binding of PDGFD and PDGFRB." (PMID 38652223, 2024).
osteosarcoma (continued). "Comparison of the contribution of each ligand-receptor pair of the PDGF signaling pathway in the non-metastatic osteosarcoma samples from the GSE152048 dataset and our sequencing samples indicated that the PDGFD-PDGFRB was the common ligand-receptor pair with a relatively large contribution." (PMID 38652223, 2024).
adrenocortical adenomas (2 papers, 2018 to 2023). "Moreover, PDGFD is highly expressed in human adrenal gland, unlike PDGFA, PDGFB, and PDGFC, and the expression of PDGFD correlates negatively with cortisol secretion in adrenocortical adenomas." (PMID 29551627, 2018).
endometrial cancer (2 papers, 2014 to 2023). Primary or metastatic malignant neoplasm involving the endometrium (mucous membrane that lines the endometrial cavity). "Recently, several studies demonstrated that platelet-derived growth factor-D (PDGF-D) play key roles in tumor growth and invasion, which might shed light on the investigations about endometrial cancer." (PMID 24646915, 2014).
epilepsy (2 papers, 2022 to 2024). A brain disorder characterized by episodes of abnormally increased neuronal discharge resulting in transient episodes of sensory or motor neurological dysfunction, or psychic dysfunction. "The pathway related to growth factors (FGF4, FGF22, and PDGFD), RTK, and PLCB4 was also associated with visual processing defects, ataxia, absence seizures, epilepsy, and Huntington's disease." (PMID 36457060, 2022).
esophageal cancer (2 papers, 2019 to 2021). A primary or metastatic malignant neoplasm involving the esophagus. "Survival univariate/multivariate COX analysis revealed that five genes, ZBTB16, AQP4, ADCYAP1R1, PDGFD, and VIPR2, and two microRNAs, miR-99a-5p, and miR-508-5p, were related to esophageal cancer prognosis." (PMID 34329340, 2021).
esophageal squamous cell carcinoma (2 papers, 2019 to 2025). Esophageal squamous cell carcinoma (ESCC) is a type of esophageal carcinoma (EC) that can affect any part of the esophagus, but is usually located in the upper or middle third. "Moreover, platelet-derived growth factor-D contributes to proliferation and invasion of esophageal squamous cell carcinoma by up-regulating NF-κB signaling pathways." (PMID 31645619, 2019).
lymph node metastases (2 papers, 2022). "ANLN and PDGFD were differentially expressed between carcinoma without and with lymph node metastasis." (PMID 36362041, 2022). "ANLN and PDGFD were significantly upregulated in CRC with lymph node metastases when compared to those without lymph node metastases and can be considered as potential biomarkers for metastases in CRC." (PMID 36362041, 2022). "Similarly to PDGFD, in our research, ANLN was upregulated in CRC with lymph node metastases when compared to normal mucosa and to CRC without lymph node metastases and positively correlated with the level of malignancy." (PMID 36362041, 2022).
mastitis (2 papers, 2018 to 2023). Inflammation of breast tissue during lactation or postpartum due to an obstructed duct or infection. "As a result, the genes MARCH3, MAST3, and PDGFD were proposed as potential causative factors for mastitis susceptibility." (PMID 36669036, 2023). "The SNP rs42550814 on BTA15:4668361, an intron variant and in significant association with recoverability from mastitis in parity 1, is located within a protein coding gene PDGFD (platelet derived growth factor D)." (PMID 29755506, 2018). "Genes involved in lymphocyte developments (e.g., MAST3 and STAB2) and genes involved in macrophage recruitment and regulation of inflammations (PDGFD and PTX3) were suggested as possible causal genes for susceptibility to – and recoverability from mastitis, respectively." (PMID 29755506, 2018). "For recoverability from mastitis we suggest EPS15L1 (essential for lymphocyte development), PDGFD (involves in macrophage recruitment and wound healing), and PTX3 (involved in regulating inflammation) as candidates for the causal genes." (PMID 29755506, 2018).
melanoma (2 papers, 2015 to 2018). A malignant, usually aggressive tumor composed of atypical, neoplastic melanocytes. "In addition, five genes (FGF10, FGF2, MITF, PDGFC, and PDGFD) were involved in “Melanoma”, which might be associated with the two-end black pigmentation observed in BMX pigs, which differs from most Chinese domestic pigs with black coats (China National Commission of Animal Genetic Resources, 2011)." (PMID 29955027, 2018). "Furthermore, B16 melanoma cells stably transfected with PDGFD increased allograft tumor growth compared with cells stably transfected with an empty vector." (PMID 25537510, 2015). "PDGFD is highly expressed in the melanoma cell line, as our findings had observed." (PMID 25537510, 2015). "Finally, we constructed a curated transcription factor (TF) and miRNA coordinated regulatory network, from which we identified downstream regulatory cascades initiated by three concordantly hypomethylated and up-regulated genes (PDGFD, ZEB1, and THRB) in NRASQ61-mutated melanomas." (PMID 25537510, 2015). "Furthermore, in order to evaluate the therapeutic potentials of PDGFD, ZEB1, and THRB, we obtained 413 melanoma samples with clinical information and gene expression from TCGA." (PMID 25537510, 2015).
meningioma (2 papers, 2014 to 2025). A generally slow growing tumor attached to the dura mater. "The few studies that have directly assessed VS and meningioma indicate similarities in NF2 gene pathogenic variants and in gene expression related to angiogenesis and tumour suppression (PDGFD, CDH1 and SLIT2)." (PMID 41437121, 2025). "DEG analysis identified 250 and 68 significantly overexpressed genes in the VS and meningioma tumour samples respectively compared to their control tissues, including six significantly co-overexpressed genes: COL1A, ERBB2, SLFN12, SLIT2, PDGFD and CDH1." (PMID 41437121, 2025).
mesothelioma (2 papers, 2016 to 2021). A usually malignant and aggressive neoplasm of the mesothelium which is often associated with exposure to asbestos. "In NCIH28 (mesothelioma), even though the potential effect of PDGFD deprivation is substantial, its cost/benefit ratio seemed low enough to prevent the invasion of the KO clone." (PMID 34359576, 2021).
renal clear cell carcinoma (2 papers, 2021 to 2022). "In addition, a previous study showed a four immune-related genes signature based on CXCL2, SEMA3G, PDGFD, and UCN is closely associated with the prognosis of renal clear cell carcinoma." (PMID 34030645, 2021).
acne (1 paper, 2023). An inflammatory process of the sebaceous glands which is characterized by comedones, nodules, papules and/or pustules on the skin. "We found that four CpG loci mediated the genetic risk of severe acne, three of which, cg03020863, cg20652636, and cg19964325, were located on the PDGFD gene body, the SH2D6 intron variant, and the 5’ UTR of the IL1R1 gene, respectively." (PMID 37554505, 2023). "Severe acne causes local skin damage, and fibroblasts are involved in this repair process, so we considered whether PDGFD also affects fibroblasts in the skin to participate in the development of inflammation and skin repair." (PMID 37554505, 2023).
acute myeloid leukemia (1 paper, 2025). Acute myeloid leukemia (AML) is a group of neoplasms arising from precursor cells committed to the myeloid cell-line differentiation. "Conversely, upregulation peaks were observed on the gene locus and adjacent noncoding region of PDGFD that is associated with the progression of various types of cancer including acute myeloid leukemia." (PMID 40181449, 2025).
adenoma (1 paper, 2022). A neoplasm arising from the epithelium. "We showed that genes ANLN, CDK1, ECT2, and TNC were associated with adenoma progression to carcinoma, ANLN and PDGFD with development of metastases, while genes ANLN, CDK1, ECT2, and PDGFD were associated with the level of malignancy." (PMID 36362041, 2022).
Adult onset (1 paper, 2021). Onset of disease manifestations in adulthood, defined here as at the age of 16 years or later. "All but one of the PDGFD variant carriers have adult-onset disease with mean age-of-onset similar to the overall cohort or IPAH alone." (PMID 33971972, 2021).
cardiac hypertrophy (1 paper, 2026). "Silencing of autotaxin, platelet-derived growth factor D, resistin and microRNA-410-5P selectively and specifically only in adipose tissue ameliorates the development of cardiac hypertrophy and fibrosis, thus preventing experimental HFpEF." (PMID 41668130, 2026).
Chagas disease (1 paper, 2024). A parasitic infection caused by Trypanosoma cruzi. "For instance, TGFβ, endothelin-1, connective tissue growth factor, and platelet-derived growth factor D (PDGF-D) are significant cytokines linked to the pathophysiology of Chagas disease." (PMID 39766337, 2024).
Crohn disease (1 paper, 2023). A gastrointestinal disorder characterized by chronic inflammation involving all layers of the intestinal wall, noncaseating granulomas affecting the intestinal wall and regional lymph nodes, and transmural fibrosis. "PDGFD, a differentially expressed gene in crypt-associated fibroblasts, has been reported to be significantly downregulated in the colonic mucosa of Crohn’s disease patients." (PMID 37080976, 2023). "Moreover, single-cell analyses of Crohn’s disease tissues revealed that γδ T cells selectively expressed PDGFD27, indicating that PDGFD might play a role in IBD." (PMID 37080976, 2023).
diffuse large B-cell lymphoma (1 paper, 2022). "It has been reported that EGFR activation contributed to PDGFD induced-ibrutinib resistance in diffuse large B-cell lymphoma (DLBCL)." (PMID 35504024, 2022).
Hypertension (1 paper, 2021). The presence of chronic increased pressure in the systemic arterial system. "Most of the FBLN2 and PDGFD variant carriers have comorbidities typical of adult IPAH patients, including hypertension, hypothyroidism, other pulmonary diseases, and metabolic diseases." (PMID 33971972, 2021).
lipid metabolism disorders (1 paper, 2023). "It was found that lipid metabolism disorders may lead to increased expression of full-length platelet-derived growth factor-D (PDGF-D) secreted into body fluids by adipose tissue." (PMID 37065745, 2023).
liver cancer (1 paper, 2024). An epithelial or non-epithelial malignant neoplasm that arises from the liver. "PDGFD has been implicated in promoting angiogenesis, proliferation, and metastasis in liver cancer." (PMID 39796131, 2024).
lymphedema (1 paper, 2022). Excess fluid collection in tissues, causing swelling. "Our results suggest that PDGFD signaling may contribute to the enhanced fibrosis and proliferation of ASCs in lymphedema." (PMID 35725971, 2022). "Notably, PDGFD–PDGFR complex interactions were significantly enhanced between some lineages (vascular endothelial cells, mast cells, NKT cells, and pericytes) and ASCs in lymphedema." (PMID 35725971, 2022).
migraine (1 paper, 2022). "Neuropeptides directly associated with pain or migraine from significantly differentially expressed neuropeptide prohormone genes include apelin (APLN), cortistatin (CORT), IGF2, neuromedin B (NMB), neuropeptide W (NPW), PDGFA and platelet-derived growth factor, D polypeptide (PDGFD), TAC4, and VIP." (PMID 35453627, 2022).
ovarian serous cystadenocarcinoma (1 paper, 2018). A malignant serous cystic epithelial neoplasm arising from the ovary. "The results showed that FBXL7 expression was positively correlated with CD44, PDGFA, PDGFC, and PDGFD in ovarian serous cystadenocarcinoma tissues with a statistical significance (p = 0.001 or p < 0.001)." (PMID 30301218, 2018). "Recent studies have shown that FBXL7 expression was positively correlated with CD44, PDGFA, PDGFC, and PDGFD in ovarian serous cystadenocarcinoma." (PMID 30301218, 2018). "In addition, FBXL7 expression was positively correlated with CD44, PDGFA, PDGFC, and PDGFD in ovarian serous cystadenocarcinoma." (PMID 30301218, 2018).
polycystic ovary syndrome (1 paper, 2023). A disorder that manifests as multiple cysts on the ovaries. "PDGFB and PDGFD decreased in the follicular fluid of PCOS patients, while ovarian administration restored follicular development and angiogenesis in a rat model of polycystic ovary syndrome." (PMID 37122871, 2023).
renal fibrosis (1 paper, 2021). A final common manifestation of a wide variety of chronic kidney diseases characterized by glomerulosclerosis and tubulointerstitial fibrosis. "Moreover, it has been reported that PDGFD is overexpressed in hepatic and renal fibrosis." (PMID 34946851, 2021).